ACTMAP (actin maturation protease)
Description:
Actin maturation protease that specifically mediates the cleavage of immature acetylated N-terminal actin, thereby contributing to actin maturation. Cleaves N-terminal acetylated methionine of immature cytoplasmic beta- and gamma-actins ACTB and ACTG1 after translation. Cleaves N-terminal acetylated cysteine of muscle alpha-actins ACTA1, ACTC1 and ACTA2 after canonical removal of N-terminal methionine (By similarity).
Synonyms: C19orf54; FLJ41131
Tractability: PROTAC: ubiquitination databases record sites on it.
Gene: Protein-coding gene on chromosome 19 (40,740,856 to 40,751,803, reverse strand). Ensembl gene ENSG00000188493.
Subcellular location: Cytoplasm
Subcellular location (Human Protein Atlas): Intermediate filaments; Centriolar satellite
Gene Ontology:
Molecular function: cysteine-type aminopeptidase activity; initiator methionyl aminopeptidase activity
Biological process: protein processing
Cellular component: cytoplasm
Genetic constraint (gnomAD): Loss-of-function variants: 27 observed, 33.38 expected, observed/expected ratio (o/e) 0.81, 90% interval 0.6 to 1.12. The upper end of that interval is the gene's LOEUF score, 1.12, which puts it in group 4 of 6, group 1 being the genes least tolerant of losing a copy. Missense variants: 472 observed, 446.72 expected, observed/expected ratio (o/e) 1.06, 90% interval 0.98 to 1.14. Synonymous variants: 206 observed, 197.97 expected, observed/expected ratio (o/e) 1.04, 90% interval 0.93 to 1.17.
Homologues: Orthologues: chimpanzee ACTMAP (98% identical), macaque ACTMAP (96% identical), pig ACTMAP (82% identical), dog ACTMAP (79% identical), rabbit ACTMAP (77% identical), rat Actmap (77% identical), mouse Actmap (76% identical), guinea pig ACTMAP (72% identical), tropical clawed frog actmap (45% identical), zebrafish actmap (40% identical), Drosophila melanogaster CG33108 (22% identical), Caenorhabditis elegans K07A1.3 (17% identical).
Diseases named in the same sentence as ACTMAP in open-access papers:
ACTMAP is named in the same sentence as 2 diseases in open-access papers, as found by Europe PMC text mining. Sharing a sentence is not in itself a finding about the gene and the disease. The quoted sentences say what the papers report.
cancer (1 paper, 2026). A tumor composed of atypical neoplastic, often pleomorphic cells that invade other tissues. "We show that (1S,3R)-tryptoline butynamides stereoselectively react with the catalytic nucleophile of ACTMAP, leading to accumulation of N-terminally unprocessed actin in cancer cells." (PMID 42159598, 2026).
ACTMAP also shares sentences with these, for which no sentence is quoted: tumor (1 paper).